S100A8 (S100 calcium binding protein A8)
Diseases named in the same sentence as S100A8 in open-access papers (continued):
Sharing a sentence is not in itself a finding about the gene and the disease.
glioma (18 papers, 2019 to 2025). A benign or malignant brain and spinal cord tumor that arises from glial cells (astrocytes, oligodendrocytes, ependymal cells). "In the literature, S100A8 expression has been shown to be associated with a worse prognosis in low-grade gliomas." (PMID 37370678, 2023). "Previous studies explored the role of S100A gene family in glioma and discovered that S100A8 was highly expressed and proved to be a marker for predicting prognosis related to immune‐based score model." (PMID 39659236, 2024). "The results showed that inhibition of S100A8 significantly increased the sensitivity of glioma cells to TMZ treatment, which further validated the important role of S100A8 in GBM for therapeutic resistance." (PMID 39659236, 2024). "Specifically, S100A8 was upregulated with the histopathologic grades of gliomas, primarily abundant in GBM and MES‐GBM subtype." (PMID 39659236, 2024). "In glioma, MDSCs are expanded and recruited by a variety of inflammatory cytokines and chemokines secreted by glioma cells and other immune cells, such as GM-CSF, S100A8/9, prostaglandin-E2 (PGE2), CCL2 and IL-8." (PMID 37234776, 2023). "In gliomas, a high expression of S100A8 and S100A9 inhibits T cell function and differentiation through interferon alpha to regulate macrophage or dendritic cell production." (PMID 37370678, 2023). "S100A8/9 can be expressed by various myloid cells and tumor cells in glioma, where it can promote tumor cell growth and migration." (PMID 35328072, 2022). "The study by Jinsheng Xiong reported that S100A8 is significantly highly expression in glioma samples." (PMID 36046652, 2022). "Glioma patients further have boosted S100A8/9 serum quantities correlated with amplified arginase bustle in serum." (PMID 35328072, 2022). "S100A8/S100A9 are also implicated in the activation of the NLRP3 inflammasome, which has been shown to play a role in glioma progression." (PMID 34975408, 2021). "In vitro experiments showed that recombinant S100A8/S100A9 proteins promoted integrin signalling dependent glioma cell migration and invasion up to a threshold level of concentrations." (PMID 30808902, 2019). "Although S100A8 had been shown to be involved in augmenting the malignant biological progression of glioma, such as proliferation, invasion, and migration, there was no specific research referring to the role of S100A8 in regulating MES phenotype transition of GSCs." (PMID 39659236, 2024). "Furthermore, there was a correlation between the secretory levels of intracellular S100A8/9 as well as an upsurge in M-MDSCs in low-grade glioma patients." (PMID 33204365, 2020). "Furthermore, there was a correlation between the secretory levels of intracellular S100A8/9 and upsurge in M-MDSCs in low-grade glioma patients." (PMID 33204365, 2020). "We have previously shown that serum from glioma patients contains increased levels of S100A8/9 compared to healthy individuals, suggesting that MDSCs in glioma patients could gain a more suppressive phenotype due to enhanced Siglec-3–S100A9 interactions." (PMID 30953118, 2019). "In addition, S100A8 and S100A9 are associated with progression and prognosis in glioma." (PMID 36046652, 2022). "Specifically, S100A8 and S100A9 were expressed in myeloid cells, S100A10 and S100A11 in various cell types, especially in glioma tumor cells, and S100A13 and S100A16 in vascular cells." (PMID 39744679, 2025). "Altogether, S100A8 and S100A9 play a significant role in proliferation, invasion, migration as well as glioma stem cell stemness via multiple target proteins and signal pathways." (PMID 36046652, 2022). "S100A3, S100A4, S100A8, and S100A9 expression was up-regulated during the progression of glioma grade." (PMID 34148033, 2021). "We observed that the IRSs of PROS1, P2RY8, PLAU, CHI3L2, MSR1, CCR5, and TRIM38 were higher than its corresponding IRSs in low-grade glioma, while the IRSs of HAMP, CARD16, and S100A8 in high-grade glioma were lower than low-grade glioma." (PMID 34954691, 2021).
glioma (continued). "High expression of S100A8 and S100A9 in glioma inhibits T cell function and their differentiation via interferon-alpha (INF-α) to regulate production of macrophages or dendritic cells." (PMID 34148033, 2021). "The significance of high levels of S100A8 and S100A9 in glioma biology was established by performing in vitro functional assays." (PMID 30808902, 2019). "To investigate the functional role of S100A8 and S100A9 in GBM microenvironment, we studied the effect of recombinant S100A8 and S100A9 on various proprieties of glioma cells." (PMID 30808902, 2019). "S100A8, S100A9 and S100B were highly expression in serum and may present as a marker correlated with survival and prognosis of glioma patients." (PMID 36046652, 2022). "Activation of NLRP3 expression by S100A8/S100A9 inhuman PBMCs increased the secretion of pro-inflammatory cytokines (IL-6, IL-1β, TNFα) and chemokines (IL-8, Gro-α, MIP-1α/β) that are prevalent in gliomas." (PMID 34975408, 2021). "Further research into the interactions between S100A8/S100A9, NLRP3, and common inflammatory cytokines may provide potential therapeutic targets for gliomas." (PMID 34975408, 2021). "Notably, the transcript levels of S100A8 and S100A9 were found to be significantly up-regulated in GBM tumors as compared to lower grade glioma and control brain tissue in multiple datasets and our cohort." (PMID 30808902, 2019). "We found S100A8 and S100A9 failed to induce glioma cell migration and invasion in cells treated with integrin inhibitory peptides (RGD)." (PMID 30808902, 2019). "Similarly, S100A8 and S100A9 proteins induced migration and invasion of U138 glioma cells at a medium, but not at a higher concentration." (PMID 30808902, 2019).
heart failure (18 papers, 2013 to 2025). Inability of the heart to pump blood at an adequate rate to meet tissue metabolic requirements. "Plasma S100A8/A9 protein levels have also been associated with left ventricular dysfunction and heart failure and can predict the risk of future cardiovascular disease events." (PMID 38062310, 2025). "We finally report causal effect of S100A8/A9 on heart failure in three independent cohorts using Mendelian randomization approach." (PMID 38538601, 2024). "S100A8/A9 is screened out through proteomic analysis, and elevated circulating S100A8/A9 is independently associated with heart failure in discovery and validation cohorts." (PMID 38538601, 2024). "The patients with high plasma S100A8/A9 levels within 24 h of an acute coronary event had higher risk of hospitalization for a main diagnosis of heart failure and reduced left ventricular ejection fractions." (PMID 33282877, 2020). "The patients with high plasma S100A8/A9 levels within 24 h of an acute coronary event had higher risk of hospitalization for a main diagnosis of heart failure and reduced left ventricular ejection fractions at 1 year after the MI." (PMID 33282877, 2020). "Due to its potential involvement in atherogenesis, plaque vulnerability, ischemia-associated myocardial inflammation, and heart failure, S100A8/A9 represents an attractive target in CVD." (PMID 24453429, 2013). "Mouse experiments have demonstrated that S100A8/A9 is actively involved in the development of heart failure secondary to ischemia/reperfusion injury and elevated S100A8/A9 concentrations are associated with increased mortality in heart failure patients." (PMID 24453429, 2013). "Therefore, elevated circulating S100A8/A9 levels have been linked to increased cardiovascular risk (such as heart failure incidence and progression) and disease severity (such us infarct size and functional impairment)." (PMID 40948795, 2025). "Thus, it is reasonable to speculate that CAD patients with repeated and sustained elevations of S100A8/A9 in response to daily stressors are at higher risk to suffer recurrent coronary events and heart failure." (PMID 29235502, 2017). "Thus, S100A8/A9 amplifies the local myocardial inflammation associated with ischemia/reperfusion injury, facilitating myocardial remodeling and the development of heart failure." (PMID 24453429, 2013). "We and others also have indicated that HP is of great significance in delaying the progression of heart failure through regulation of several signaling effectors such as activation of S100A8/A9 and reduced ERK1/2 activation." (PMID 33842546, 2021). "Recombinant S100A8/A9 treatment increases myocardial injuryand exacerbates heart failure in a mouse I/R model." (PMID 32696819, 2020). "S100A8/A9 was found to be increased in patients suffering from severe heart failure (NYHA class III-IV) compared to patients with hypertension or healthy subjects, in a group of elderly individuals (>70 years of age)." (PMID 24453429, 2013). "In the heart failure group, S100A8/A9 was positively correlated with IL-6 and IL-8 and predicted all-cause mortality in 1 year." (PMID 24453429, 2013). "In a murine heart failure model it was demonstrated that S100A8/A9 proteins also activate the receptor for advanced glycation end products (RAGE)." (PMID 23874727, 2013). "Suppression of S100A8/A9 protein expression has been shown to exhibit significant anti-inflammatory and protective effects against myocardial hypertrophy and fibrosis across various tissues, thereby mitigating the progression of heart failure (HF)." (PMID 39175627, 2024). "In potentiating myocardial injury, S100A8/A9 may be related to promoting inflammation progression, inducing mitochondrial dysfunction, managing heart failure progression, and regulating autophagy and apoptosis." (PMID 39329929, 2024). "Additionally, the S100a8/S100a9 complex is a useful biomarker for elderly patients with severe heart failure." (PMID 35907209, 2022).
heart failure (continued). "Robust prospective clinical studies are required to explore whether S100A8/A9 is involved in the pathogenesis of heart failure in humans and whether plasma S100A8/A9 levels in the pre- and post-infarct period are associated with loss of cardiac function." (PMID 24453429, 2013). "However, the specific mechanisms by which S100A8/A9 differentially regulates cardiac fibrosis and heart failure remain unclear." (PMID 39329929, 2024). "S100A8 has not been previously associated with HFpEF but has been linked to advanced heart failure." (PMID 26792056, 2016). "However, it is unclear whether progressive heart disease was the main cause of death in this group and it remains to be determined whether S100A8/A9 is actively involved in the pathogenesis of heart failure in humans." (PMID 24453429, 2013). "Recent human studies have suggested that S100A8/A9 levels were elevated in type 2 diabetic patients and indeed, the S100A8/S100A9 complex could be an useful biomarker for the prediction of 1-year mortality in elderly patients with severe heart failure." (PMID 27547188, 2016). "Similarly, S100A8/A9 binding to RAGE leads to MAP kinase phosphorylation and NF-kB activation, promoting leukocyte production in the bone marrow, carcinogenesis, cardiomyocyte dysfunction and postischemic heart failure." (PMID 24453429, 2013).
Autoimmunity (17 papers, 2012 to 2025). The occurrence of an immune reaction against the organism's own cells or tissues. "Running contrary to the apparent anti-inflammatory function in cancer, the S100A8, S100A9 and S100A8/A9 were also reported to mediate chemotactic and pro-inflammatory responses in infection and autoimmunity." (PMID 39497822, 2024). "Elevated levels of S100A8/A9 heterodimers have been reported in inflammatory diseases, cancers, and autoimmunity." (PMID 25948779, 2015). "Increased expression of S100A8/A9 is reported in inflammatory diseases, cancer, cardiovascular disease, and autoimmunity." (PMID 25948779, 2015). "S100A8 (MRP8) and S100A9 (MRP14) are commonly found as a heterodimer called calprotectin that binds Ca2+ and Zn2+ ions and plays an important role in inflammation caused by infection, autoimmunity or metabolic diseases." (PMID 35842572, 2022). "In a murine model of autoimmunity, the lack of S100A8 and S100A9 was associated with a reduction of IL-17 release from autoreactive CD8 + T cells and with lower autoantibody production." (PMID 34867240, 2021). "Moreover, S100A8/9 contributed to TLR7-mediated autoimmunity." (PMID 38429401, 2024). "Furthermore, some reports indicate that S100A8/S100A9 released from inflamed tissue could enter systemic circulation and enhance susceptibility of distinct organ systems for autoimmunity and inflammatory disorders." (PMID 26661255, 2015). "Extracellular S100A8/S100A9 act as danger signal and amplify the inflammatory responses in infection, autoimmunity and cancer." (PMID 26661255, 2015). "We have recently demonstrated, that S100A8/A9 complexes are endogenous activators of TLR4 and via this signaling pathway they promote inflammatory processes in infections and autoimmunity." (PMID 22489132, 2012). "S100A8 is an mRNA targeted by ENSRNOT00000078133, a major leukocyte protein secreted by activated leukocytes, and binds to Toll-like receptor 4 to promote inflammation and autoimmunity." (PMID 36434596, 2022). "This newly identified connection between the local production of S100A8/A9 as DAMP molecules and autoimmunity may have direct implications for many other chronic inflammatory diseases." (PMID 22489132, 2012).
Crohn disease (17 papers, 2015 to 2025). A gastrointestinal disorder characterized by chronic inflammation involving all layers of the intestinal wall, noncaseating granulomas affecting the intestinal wall and regional lymph nodes, and transmural fibrosis. "S100A8 activates neutrophil chemotaxis and contributes to an enhanced immune response and tissue damage in Crohn’s disease." (PMID 40363705, 2025). "S100A9 is best known as a dimerization partner of S100A8, forming calprotectin, which is used as an effective marker of gut inflammation in patients with Crohn’s disease and ulcerative colitis." (PMID 34884728, 2021). "For example, in the treatment of femoral head osteoarthritis, it reduces serum levels of S100A9 protein, thus contributing to improved tissue vascularisation, while in Crohn’s disease, it has a down-regulating effect on S100A8/S100A9 heterotetramers (calprotectin)." (PMID 40243713, 2025). "The S100A8/A9 complex, known as calprotectin, is used as a biomarker for IBD, including Crohn’s disease and ulcerative colitis." (PMID 38979413, 2024). "This bioinformatic study elucidates S100A8, S100A9, S100A12 and CXCR2 as hub genes for the co-occurrence of Crohn’s disease and peripheral artery disease." (PMID 35795659, 2022). "Measurement of S100A8/S100A9 in feces is considered a reliable method to distinguish IBD patients from those without chronic intestinal inflammation and it is, together with serum levels of S100A8/S100A9, useful in monitoring inflammation in patients with Crohn’s disease or ulcerative colitis." (PMID 37372165, 2023).
type 2 diabetes (17 papers, 2009 to 2025). "TLR9 message and protein expression levels which are higher in diabetic wounds compared to control wounds have been linked to impaired wound healing in type 2 diabetes mellitus (T2DM) cases via the induction of pro-inflammatory S100A8 and IL-8." (PMID 33519463, 2020). "In a transcriptome analysis of peripheral blood neutrophils from patients with type 2 diabetes compared to healthy controls, S100A8 was among the most significantly upregulated factors in diabetic patients." (PMID 38153746, 2023). "Circulating levels of S100A8 and visceral adiposity expression are also elevated in obese patients with type 2 diabetes." (PMID 37497233, 2023). "The levels of S100A8, which is derived mainly from neutrophils regarded as a mediator of inflammation, were higher in neutrophils from type 2 diabetes patients than in those from healthy controls (P = 0.019)." (PMID 32377527, 2020). "This association with vascular risk supports previous reports of low sRAGE and high S100A8/A9 and S100A12 levels in patients with type 1 and type 2 diabetes, and essential hypertension." (PMID 19284577, 2009). "Moreover, platelet numbers are increased in type 2 diabetic mellitus (T2DM) patients by neutrophil S100A8/A9 secretion." (PMID 35039631, 2022). "Furthermore, qPCR of genes related to neutrophil activation revealed that the expression of SELL, SELP, CXCR1, and S100A8 was significantly increased in neutrophils from type 2 diabetes patients compared with that in neutrophils from controls." (PMID 32377527, 2020). "Therapeutic strategies to reduce neutrophilia and NETosis are aimed at disruption of S100A8/S100A9 signalling or their downstream mediators in neutrophils, thus suppressing excessive granulopoiesis as seen in type 2 diabetes." (PMID 39875729, 2025). "After merging and filtering across datasets, 13 genes were found to be consistently upregulated in both ulcerative colitis and type 2 diabetes, with CXCL9, S100A8, CXCL10, CHI3L1, and SLC6A14 showing the most significant alterations." (PMID 41155631, 2025).
cystic fibrosis (15 papers, 2006 to 2023). Autosomal recessive disorder caused by pathogenic variants in the CFTR gene (cystic fibrosis transmembrane conductance regulator), which encodes a chloride and bicarbonate channel expressed in epithelial cells, and follow the diagnosis criteria. "Indeed in sputum of cystic fibrosis and chronic obstructive pulmonary disease patients, higher levels of S100A8/A9 were observed." (PMID 32582175, 2020). "Also, elevated levels of S100A8/A9 in plasma of cystic fibrosis patients compared to healthy controls were found and the high levels correlated with high sputum production and C-reactive protein." (PMID 29180999, 2017). "Another study comparing acute respiratory distress syndrome (ARDS), cystic fibrosis, and COPD suggests that S100A8 and S100A9 are linked to chronic inflammation while S100A12 is linked to acute inflammation." (PMID 26464846, 2013). "A number of studies have identified PTMs on the S100A8 and S100A9 subunits detected in specimens from humans including saliva, bronchial lavage fluid (BALF), sputum from cystic fibrosis patients, serum, plasma, nasal mucus, pimple pus, and kidney stones." (PMID 36826733, 2023). "Moreover, it was demonstrated that despite similarly elevated levels of S100A8/A9, S100A12 was more increased in ARDS compared to levels in BALF obtained from cystic fibrosis patients." (PMID 23874727, 2013).